SCARNA6 (small Cajal body-specific RNA 6)
Synonyms: U88
Gene: Small Cajal body-specific RNA gene on chromosome 2 (233,288,676 to 233,288,940, forward strand). Ensembl gene ENSG00000251791.
Gene Ontology:
Biological process: RNA processing
Cellular component: nucleolus
Homologues: Orthologues: chimpanzee SCARNA6 (99% identical), rabbit SCARNA6 (72% identical).
Diseases named in the same sentence as SCARNA6 in open-access papers:
SCARNA6 is named in the same sentence as 1 disease in open-access papers, as found by Europe PMC text mining. Sharing a sentence is not in itself a finding about the gene and the disease.
SCARNA6 shares sentences with these, for which no sentence is quoted: Stroke (1 paper).